HDAC3 (histone deacetylase 3)
Diseases named in the same sentence as HDAC3 in open-access papers (continued):
Sharing a sentence is not in itself a finding about the gene and the disease.
tumor (continued). "HDAC inhibitors as single agents, via modulation of HDAC1, HDAC3, HDAC8 and HDAC10 function, increased the expression of MHCA and decreased the expression of PD-L1, PD-L2 and ODC on tumor cells." (PMID 29137331, 2017). "Down-regulation of SOCS1 decreased the expression of HDAC3, TGaseII and COX-2 and inhibited the interactions of FcεRIβ with Lyn, HDAC3 and SOCS1 in tumor tissue." (PMID 28968979, 2017). "We used a CCA cell tumor xenograft model to evaluate the in vivo anticancer and HDAC3 inhibitory activity of MI192, and found that MI192 administration significantly inhibited tumor growth." (PMID 28569784, 2017). "When we assessed the expression of HDAC3 on nine pairs of CCA tissues, we found that HDAC3 significantly promoted in tumor tissues compared with adjacent tissues." (PMID 28569784, 2017). "HDAC protein expression was then assayed by Western blot (WB), and the expression of HDAC2, HDAC3, and HDAC8 were higher in CCA tissues compared with paired non-tumor tissues (P<0.05)." (PMID 27705912, 2016). "Among HDACs 1-10, class I HDACs (HDAC1, HDAC2, HDAC3, and HDAC8) and HDAC9 were more highly expressed in CCA tissues compared with paired non-tumor tissues (P<0.05)." (PMID 27705912, 2016). "Multivariate analysis showed that nuclear HDAC3 and cytoplasmic CDH1 (P = 0.001 and P = 0.010, respectively), as well as tumor differentiation (P = 0.009) are independent prognostic factors." (PMID 26918727, 2016). "We selected HDAC2, HDAC3, and HDAC8 to further examine in 79 paraformaldehyde-fixed, paraffin-embedded paired CCA and adjacent non-tumor tissues with immunohistochemistry (IHC)." (PMID 27705912, 2016). "CCA tissues had higher expression compared with corresponding matched non-tumor tissues (27.85%, 30.38%, and 32.91% for HDAC2, HDAC3 and HDAC8, respectively; χ2 =10.505, 10.327, 6.609; P<0.05)." (PMID 27705912, 2016). "The maturation of INPs requires Numb, the NHL family protein Brain tumor (Brat), the transcription factor Earmuff (Erm), as well as the BAP and Histone deacetylase 3 (HDAC3) chromatin remodeling complexes." (PMID 25285448, 2014). "For HDAC-1 40% of the tumours showed high expression levels, for HDAC-2 42% and for HDAC-3 even 59%." (PMID 24624923, 2014). "HDAC3 siRNA abrogated the ability of VPA to modulate AKT phosphorylation, to suppress tumor cell growth and to induce autophagy." (PMID 23866964, 2013). "HDACs such as HDAC1, HDAC3, and HDAC6 are frequently overexpressed in solid tumors, promoting malignant phenotypes through the repression of tumor suppressor genes, enhancement of epithelial–mesenchymal transition (EMT), immune evasion, and increased angiogenesis." (PMID 41150792, 2025). "Based on the protein interaction between USP38 and HDAC3, we believe that the regulation and activation of the USP38/HDAC3 signaling axis may be common across multiple tumor types." (PMID 40936898, 2025). "To investigate the potential impact of IHCH9033 treatment on AML patients, we executed comparable gene expression analysis of these class I HDAC members between AML tumor and normal tissues, revealing that HDAC1, HDAC2 and HDAC3 were notably overexpressed in AML." (PMID 39955584, 2025). "In studies on mouse colon adenocarcinoma cells MC38 and fibrosarcoma tumor cells MCA205, Li and colleagues found that HDAC3 inhibitors (such as vorinostat and romidepsin) can suppress the expression of CXCL9, CXCL10, and CXCL11 by directly affecting the binding in the promoter region." (PMID 40573881, 2025). "Additionally, tucidinostat, by inhibiting HDAC3, in combination with chiglitazar, led to synergistic ferroptotic cell death in LSC-like cell lines and primary CD34+ LSCs, ultimately reducing tumor growth in a PDX model." (PMID 39955584, 2025). "Furthermore, PD-L1 expression in dendritic cells in the TME and PD-L1 transcription in tumour cells are elevated through increased interferon -γ (IFN-γ) production and acetylation of PD-L1 promoter region histone after HDAC3 expression inhibition." (PMID 38541208, 2024).
tumor (continued). "Altogether, these data suggest that MC4448 is a new potent and highly tumor-specific HDAC3 inhibitor that hampers FP-RMS tumor cell survival at nM doses without affecting normal cells." (PMID 39107280, 2024). "Mechanistically, HDAC3 inhibition has been demonstrated to derepress BCL6-repressed interferon (IFN) responses and antigen-presenting genes and enhance the killing effects of tumor-infiltrating lymphocytes." (PMID 39117798, 2024). "To elucidate whether the effect of HDAC3 on HCC is regulated by oestrogen, we performed ovariectomy (OVX) on HDAC3LCKO female mice and examined tumour progression." (PMID 37752418, 2023). "During the GBM process, hyperactivity of HDAC3, 5, and 9 is expressed in IL-4-induced M2 GAMs that increase the levels of TGFβ and IL-10, resulting in exacerbating the immunosuppressive capacity of GBM tumor cells." (PMID 35572545, 2022). "Furthermore, either HDAC3 specific inhibitor RGFP966 or glutamine uptake inhibitor V9302 delayed the tumor growth, and the combination of RGFP966 and V9302 led the tumor partial or complete regression in vivo." (PMID 35187863, 2022). "Importantly, high HDAC3 expression in GC tissue correlates with high FTO and MYC expression, an advanced tumor state and lower survival probability." (PMID 36358890, 2022). "Apicidin downregulates HDAC3 and HDAC4 and suppresses the tumor growth of transplanted Ishikawa cells, the expression of proliferative cell nuclear antigen (PCNA), and vascular endothelial growth factor (VEGF) in tumor xenograft model, respectively." (PMID 34804263, 2021). "HDAC3 knockout in 381 T ERMS cells significantly inhibited cell proliferation in vitro and tumor growth in vivo, and resulted in extensive tumor differentiation in xenograft mice, suggesting the potential value of CRISPR/CAS9 technology in RSM differentiation-induction therapy." (PMID 33546657, 2021). "More specifically, HDAC-2 and HDAC-3 proteins were correlated with a lower grade of tumor differentiation and negative estrogen receptor (ER) and progesterone receptor (PR) status." (PMID 34441281, 2021). "On the whole, the present study has pictured the mechanisms of HDAC3, TGIF1, TGFβ signaling pathway and miR-296-3p in CRC that knockdown of HDAC3 or TGIF1 or up-regulation of miR-296-3p blocks CRC development and tumor growth via inhibiting TGFβ signaling pathway." (PMID 33203425, 2020). "Furthermore, murine xenograft tumor models were used to verify the role of JNK/c-Jun and HDAC3 in PD-L1 expression in A549/CDDP cells in vivo." (PMID 32024543, 2020). "Hence, the study is intended to probe into the mechanism translation of HDAC3, miR-296-3p, TGFβ signaling pathway and TGIF1 in CRC and it is elucidated that HDAC3 deteriorates CRC progression and promotes tumor growth via miR-296-3p/TGIF1/TGFβ axis." (PMID 33203425, 2020). "Determination of the expression pattern of HDAC class I‐IV family members in the tumor (2102EP) and endothelial cells (Ea.hy926) used in this study revealed that the class I family members HDAC1, HDAC2, and HDAC3 are the primarily expressed HDACs in both cell lines." (PMID 31583820, 2019). "Our findings suggest clear differences between the anti-tumor inflammatory macrophages induced by the class II HDACi TMP195 and antimicrobial macrophages induced by HDAC3 targeting inhibitors suggesting a concept of differential imprinting of macrophage function via selective HDAC inhibition." (PMID 30683619, 2019). "They showed that HDAC3 is aberrantly co-expressed with pSTAT3 Tyr705 in DLBCL tumor samples but not in normal blood B-cells and that HDAC3 complexed with STAT3 in pSTAT3 Tyr705-positive DLBCL cell lines (i.e., Ly3 and DHL2)." (PMID 29914167, 2018). "Because HDAC3 is a critical regulator of STAT3 signaling during liver regeneration, we investigated whether elevated HDAC3 in HCC was correlated with a higher tumor cell proliferation rate." (PMID 29540666, 2018).
tumor (continued). "Our study was performed to evaluate the anti-tumor activity of crotonoside and found that crotonoside could inhibit all of FLT3 and HDAC3/6, and exhibited selective inhibition pattern toward AML cells." (PMID 29262547, 2017). "In this study, we found HDAC3 in the cytoplasm and nucleus of tumor cells, but not on the plasma membrane." (PMID 26918727, 2016). "Probing various publicly available datasets (GSE20347, GSE47404, GSE13937) to assess the expression of SOX4, EZH2 and HDAC3 in primary esophageal squamous and adenocarcinoma samples, we found SOX4 and EZH2 to be significantly upregulated in ESCC tumor samples (GSE20347), compared to normal tissues." (PMID 25644061, 2015). "This may lead to tumor progression and the metastasis of EAC and ESCC; SOX4, EZH2, HDAC3 and miR-31 emerge as potential therapeutic targets." (PMID 25644061, 2015). "The positive role of HDAC3 in the growth and progression of HCC is further supported by the inhibitory experiment, in which the downregulation of HDAC3 results in a strong anti-tumor effect and enhances the efficacy of chemotherapeutic agents in HCC." (PMID 25623232, 2015). "Finally, using western blot we confirmed that HDAC1, HDAC2, HDAC3 and COX-2 are expressed in the BxPC-3 CAM tumor." (PMID 24040391, 2013). "HDAC1 (P=0.006) and HDAC2 (P=0.047) expression but not HDAC3 (P=0.584) expression correlated positively with Gleason scores, with high-grade tumours expressing both isoforms at higher rates." (PMID 18212746, 2008). "Notably, PCAF promoted, whereas AARS1 did not affect, RHOA lactylation, highlighting the substrate-dependent regulation of lactylation; HDAC3 acts as a metabolic checkpoint, dynamically balancing lactylation levels to modulate RHOA signaling in tumor microenvironments." (PMID 41291745, 2025). "HDAC3 is the principal isoform controlling PD-L1 expression: its inhibition increases IFN-γ production and histone acetylation at the PD-L1 promoter, thereby enhancing PD-L1 transcription in tumor cells and elevating PD-L1 levels in dendritic cells within the tumor microenvironment." (PMID 41303477, 2025). "Given the activated IFN signature observed in the combined GNAS KO plus RGFP966 condition and the critical role of IFN signaling in anti-tumor immune responses, we explored whether GNAS KO can synergize with HDAC3 inhibition to promote anti-tumor immunity such as CD8+ T cell-induced cytotoxicity." (PMID 39117798, 2024). "Also, HDAC1, HDAC2, and HDAC3 play a regulatory role in restricting the transcription of STAT3 target genes within another commonly altered pathway, the JAK/STAT pathway, resulting in subsequent epigenetic silencing of tumor-suppressor genes." (PMID 39409979, 2024). "Moreover, HDAC3 KO also hampers tumor growth in vivo in the absence of and more efficiently after IR." (PMID 39107280, 2024). "Thus, a set of four publications present a pro-tumor function of HDAC3 with worse prognosis, opposing one study where no variation in its expression was observed." (PMID 36358890, 2022). "In addition, suppression of HDAC3 also resulted in the upregulation of MEG3, a lncRNA tumor suppressor specifically silenced in NFPAs, as well as components in the Rb signaling pathway such as P16 and E2F1, both of which have been suggested to be involved in the pathogenesis of NFPAs." (PMID 35646715, 2022). "Additionally, owing to the scarcity of literature on the relationship between HDAC3 and TGIF1, further investigation is still required so as to validate the established promoting effect of HDAC3 on ESCC cell malignant phenotypes and tumor growth through blockade of miR-494-mediated TGIF1 inhibition." (PMID 35578338, 2022).
tumor (continued). "At four weeks post inoculation, mice bearing HDAC3 KO tumor showed impaired engraftment (50% vs. 25% non-engrafted tumor in HDAC3 KO and HDAC3 WT group, respectively) and decreased tumor burden (mean total flux 1.1e7 vs. 2.9e9 in HDAC3 KO and WT, respectively)." (PMID 31142847, 2020). "Depleted HDAC3 elevated miR-296-3p expression and reduced TGIF1 expression, decreased TGFβ pathway-related proteins, inhibited CRC proliferation, invasion, and migration in vitro and slowed down tumor growth and induction of apoptosis in vivo, which were reversed by miR-296-3p knockdown." (PMID 33203425, 2020). "Because of this epigenetic dysregulation involving overexpression of HDAC1, HDAC2, HDAC3, and LSD1, we anticipate that the 4SC-202, which specifically targets Class I HDACs (HDAC1, HDAC2, HDAC3, HDAC8) and LSD1, may selectively affect ATRT tumor cells." (PMID 32210076, 2020). "Kim’s lab also found that miR-326 could regulate the tumor-induced angiogenesis through targeting HDAC3, and there was a negative feedback loop between HDAC3 and miR-326." (PMID 31730013, 2019). "Moreover, the combined expression of H2AFJ and HDAC3 was appeared to be inversely correlated with the time to new tumor event after TMZ therapy in the wild-type IDH1/non-G-CIMP GBM patients." (PMID 31906036, 2019). "Due to this role in DNA damage, selective HDAC3 inhibition could potentially target the rapidly proliferating tumor cells while not harming the surrounding quiescent, non-malignant cells." (PMID 23894374, 2013). "Furthermore, the immunogenicity of epithelial tumour cells was increased by TSA via upregulating UL16-binding protein (ULBP) expression (an NKG2D ligand) and enhancing NK cell-mediated tumour cytotoxicity related to the release of HDAC3 from the ULPB promoter." (PMID 22461998, 2012). "Furthermore, HDAC3LCKO&IL-6−/− female mice developed more and larger tumours than HDAC3LCKO female mice, implying that HDAC3 deletion may amplify the negative effects of IL-6 deficiency." (PMID 37752418, 2023). "Specifically, MYC showed positive correlations with oncogenic factors HDAC2, HDAC3, AKT2, and AKT3, while demonstrating negative correlations with tumor suppressors PTEN and FOXO1." (PMID 40229260, 2025). "While HDAC2, HDAC3 and HDAC6 showed increased protein levels, the RNA levels either did not change (HDAC2 and HDAC3) or even decreased (HDAC6) in tumor samples." (PMID 23951168, 2013). "Indeed, the combination of HDAC3 inhibitor RGFP966 with a DNA demethylation reagent, 5-aza-2-deoxycytidine, synergistically enhanced the expression of several tumor suppressors such as p16, PTEN, STAT1, CD40, and large non-coding RNA MEG3, accompanied by growth suppression." (PMID 35646715, 2022).
infection (19 papers, 2008 to 2025). The state of being infected such as from the introduction of a foreign agent such as serum, vaccine, antigenic substance or organism. "More importantly, we have demonstrated that mice with macrophage specific HDAC3 knockout are more susceptible to infection with bacteria such as pseudomonas aeruginosa." (PMID 35658939, 2022). "Degradation of RIP1 resulted from elevated expression of Ctsb in HDAC3 deficient macrophages impaired TNFα mediated NF-κB activation and eventually impaired the inflammatory response and anti-infection immunity of host." (PMID 35658939, 2022). "HDAC3-deficient mice produced decreased levels of serum IFN-β in response to infection with VSV or HSV than their HDAC3fl/fl littermates." (PMID 32772249, 2021). "Specifically, treatment with an HDAC3 inhibitor significantly suppressed HCV replication in a murine infection model, providing direct evidence for HDAC3’s involvement in facilitating viral propagation." (PMID 40918255, 2025). "We found that the histone H3 deacetylase HDAC3, via regulation of ergosterol production for tolerance to oxidative stress, not only regulated the infection of insects but also the development of the symbiotic relationship with plants." (PMID 39287372, 2024). "Mechanistically, butyrate upregulates reactive oxygen species (ROS) levels after macrophage infection with Leptospira by inhibiting HDAC3." (PMID 39287437, 2024). "To better characterize early events responsible for the effects of HDAC3 silencing, we performed a kinetic analysis of gene expression upon infection with shHDAC3 adenovirus." (PMID 34502211, 2021). "Efficient depletion of Hdacs1,2 and Hdac3 were observed in these cells following infection with an adenovirus-containing Cre recombinase (Ad-Cre)." (PMID 23947532, 2013). "We observed that infection of Namalwa cells by SeV resulted in a strong and transient increase in HDAC3 mRNA and protein levels at 9–16 h p.i." (PMID 22685561, 2012). "We found that HDAC3 is predominantly responsible for deacetylation during MtbPrt infection." (PMID 34381738, 2021). "Depletion of HDAC8 and HDAC3 resulted in decreased infection by IAV." (PMID 22046129, 2011). "HDAC3-mediated deacetylation of TBK1 at Lys241 and Lys692 occurred during the late stage after SeV challenge (5 hours post-infection)." (PMID 32772249, 2021). "We measured CX3CL1 mRNA levels in cells following infection in the presence of HDAC inhibitors, TSA (for HDAC1/2) and EX527 (for HDAC3 type Sirt1)." (PMID 23724129, 2013). "Beginning at approximately 14 h after infection, decreased levels of IFN-A mRNA correlated with decreased histone H3K9 and H3K14 acetylation and recruitment of HDAC3 to IFN-A gene promoters." (PMID 22685561, 2012). "Expression of several histone deacetylases was also regulated during infection: HDAC2 and HDAC10 expression levels increased, while HDAC3, HDAC6, and HDAC9 expression decreased." (PMID 18331636, 2008). "However, infection with a higher dose of bacteria (1,000 c.f.u.)yielded opposite data with increased recruitment of NCOR/HDAC3 and decreased recruitment of p300." (PMID 28074841, 2017). "Notably, although NcoR2 and HDAC3 remained at a high level over the infection period, they failed to reside on IRF7 promoter and hinder its transcription when Bcl6 expression was suppressed by miR-127." (PMID 26728228, 2016). "Interestingly, lower expression levels of HDAC3, 5, 10, and 11 were not seen at early timepoints after infection with Mtb-GC1237, a virulent Beijing strain, implying that this could be advantageous to the pathogen." (PMID 32117228, 2020).